SHANK3 (SH3 and multiple ankyrin repeat domains 3)
Diseases named in the same sentence as SHANK3 in open-access papers (continued):
Sharing a sentence is not in itself a finding about the gene and the disease.
Phelan-McDermid syndrome (continued). "SHANK3 mutations and chromosomal rearrangements at 22q13.3 can cause Phelan-McDermid syndrome." (PMID 36768153, 2023). "Mutations in the SHANK3 gene can lead to Phelan McDermid syndrome." (PMID 37035742, 2023). "However, our findings are consistent with other mouse models of ASD including SHANK3 mutants (associated with Phelan-McDermid syndrome) and Fmr1 mutants (associated with Fragile-X Syndrome), which also show no impairment in PPI." (PMID 37649973, 2023). "ASD and Phelan-McDermid syndrome are linked to SHANK3 mutations." (PMID 36768153, 2023). "Mutations of SHANK3 are associated with the Phelan-McDermid syndrome and ASD." (PMID 36970280, 2023). "SHANK3 is the most recognized member of the family, being associated with Phelan-McDermid syndrome." (PMID 36142719, 2022). "Interestingly, macrocephaly has been associated with SHANK3 mutations and Phelan-McDermid syndrome (PMDS)." (PMID 34899182, 2021). "Phelan-McDermid syndrome (PMS) is a neurodevelopmental disorder associated with a terminal deletion affecting chromosome 22 (22q13) that results in the loss of function of the SHANK3 gene." (PMID 26306707, 2015). "The SHANK3 gene codes for a protein that plays a critical role in synaptic function by scaffolding the postsynaptic density of glutamatergic synapses and its loss is sufficient to cause Phelan-McDermid syndrome (PMS)." (PMID 25685306, 2014). "Thus, the phenotypic variability of the Phelan-McDermid syndrome, which was considered to result from the wide range of deletion sizes, was also observed for individuals carrying SHANK3 de novo or truncating mutations." (PMID 25188300, 2014). "SHANK3 is the critical gene for the core neurological and behavioral symptoms in this syndrome, as the loss of one copy (haploinsufficiency) of SHANK3, occurring through intragenic deletion or point mutation, is sufficient to cause the neurobehavioral manifestations of Phelan-McDermid syndrome." (PMID 23758760, 2013). "In addition, impairments in HDAC are involved in SHANK3 mutations in Phelan-McDermid syndrome." (PMID 37873949, 2024). "Interestingly, in a group of seven patients with Phelan-McDermid syndrome (22q13.3 deletion, which is associated with a deletion of the SHANK3 gene), four showed the presence of bipolar depression, which suggests a close relationship between Shank3 and this disorder." (PMID 36232725, 2022). "Phelan-McDermid Syndrome (PMS), primarily linked to SHANK3 haploinsufficiency, presents with complex neurodevelopmental features, including developmental regression, whose underlying mechanisms are poorly understood." (PMID 41620577, 2026). "We present a family case study of Phelan-McDermid syndrome (PMS), a neurodevelopmental disorder caused by haploinsufficiency of the SHANK3 gene, in which two of three siblings were clinically diagnosed with PMS." (PMID 41683985, 2026). "Background/Objectives: Phelan-McDermid syndrome (PMS), caused by either chromosome 22q13.3 deletions or pathogenic/likely pathogenic variants in the SHANK3 gene, is a rare neurodevelopmental disorder." (PMID 41751586, 2026). "Haploinsufficiency of the Shank3 gene manifests in Phelan-McDermid Syndrome (PMS), a monogenetic form of ASD." (PMID 40313537, 2025). "An age-matched sample of participants with SHANK3 haploinsufficiency (Phelan-McDermid syndrome, PMS) was used to compare adaptive behavior between the two groups." (PMID 40307697, 2025). "Phelan-McDermid Syndrome (PMS) is a rare genetic condition characterized by deletion or mutation of region 22q13.3, which includes the SHANK3 gene." (PMID 40855273, 2025). "Phelan-McDermid syndrome (PMDS) arises from mutations in the terminal region of chromosome 22q13, impacting the SHANK3 gene." (PMID 38858349, 2024). "Patients with Phelan-McDermid syndrome, which have only one copy of the Shank3 gene, suffer from developmental delay, hypotonia, delayed or absent speech, and autistic symptoms such as restricted and repetitive behaviors." (PMID 38486049, 2024).
Phelan-McDermid syndrome (continued). "With such limitations, a simple and cost-effective PCR based test for SHANK3 deletion can be an effective tool for screening–especially for patients showing Phelan-McDermid syndrome (depending on examination results from neuropsychiatrist)." (PMID 38451970, 2024). "Shank3 gene mutations cause several neuronal developmental disorders, such as ASD, Phelan-McDermid syndrome (PMS), schizophrenia and intellectual disability (ID)." (PMID 38486049, 2024). "Haploinsufficiency of SHANK3, arising from mutations or deletions that disrupt SHANK3 protein expression or function is identified in a notable proportion (0.5-2%) of individuals with ASD and is the cause of Phelan-McDermid syndrome (PMS, 22q13.3 deletion)." (PMID 39633421, 2024). "This study contributes new insights into SHANK3 skeletal muscle pathology, and further highlights prospective targets for treatment of hypotonia in Phelan-McDermid syndrome." (PMID 37745298, 2023). "This is even more surprising considering that the SHANK3 protein is enriched in the DS and that available evidence in human patients with Phelan-McDermid syndrome points at major alterations in the DS." (PMID 36970280, 2023). "SHANK3-haploinsufficiency is reported in Phelan-McDermid syndrome, a rare condition characterized by ID, hypotonia, global developmental delay, and ASD, among other features." (PMID 38137073, 2023). "Phelan-McDermid Syndrome (PMS), is caused by the loss of one or more nucleotides in the DNA sequence near the end segment of chromosome 22 that disrupts the SHANK3 gene and the synthesis of the SHANK3 protein." (PMID 36670624, 2022). "Individuals with a SHANK3-related neurodevelopmental disorder, also termed Phelan-McDermid syndrome or abbreviated as PMS, exhibit significant global developmental delay, language impairment, and muscular hypotonia." (PMID 36699652, 2022). "Phelan-McDermid Syndrome (PMS) is a well-characterized genetic condition that results from haploinsufficiency of SHANK3 in the 22q13.3 region." (PMID 33910615, 2021). "SHANK gene mutations are highly associated with ASD and more specifically the Phelan-McDermid syndrome (PMDS), which is caused by heterozygous 22q13.3-deletion resulting in SHANK3-haploinsufficiency, or by SHANK3 missense variants." (PMID 34784886, 2021). "The female proband AB133 has a terminal de novo deletion involving the distal part of chromosome 22q13.33 that includes the SHANK3 gene, considered the culprit gene for the Phelan-McDermid syndrome (PMS)." (PMID 32081867, 2020). "A specific form of a Shank3-dependent developmental disorder is Phelan-McDermid syndrome (PMS), which is also known as 22q13.3 deletion syndrome, with a deletion or single mutation in one copy of the Shank3 gene." (PMID 30971895, 2019). "SHANK3 is deleted in Phelan-McDermid syndrome, a disorder that is frequently comorbid with ASD and recurrent mutations in the SHANK3 gene have been identified in individuals with ASD." (PMID 31860442, 2019). "Phelan-McDermid syndrome, which oftentimes goes along with a syndromal variant of ASD, is a SHANK3 deficiency disorder and patients frequently have low zinc levels, which can be a modifying factor of their phenotype." (PMID 30853900, 2019). "Here, we investigate the physiological basis for GI distress in ASD by studying gut function in a zebrafish model of Phelan-McDermid syndrome (PMS), a condition caused by mutations in the SHANK3 gene." (PMID 30733854, 2019). "In this study, we examined sleep in Phelan-McDermid syndrome (PMS) patients with SHANK3 mutations and in a mutant mouse with a deletion in Shank3 exon 21 (Shank3ΔC)." (PMID 30973326, 2019). "Heterozygous contiguous gene deletion at 22q13 or mutations in the SHANK3 gene (OMIM 606230), located within the minimum critical region, cause Phelan-McDermid syndrome (PHMDS, OMIM 606232)." (PMID 29736186, 2018).
Phelan-McDermid syndrome (continued). "Rats with changes in the SHANK3 gene will be a useful tool for future research into Phelan-McDermid syndrome, particularly in understanding how it affects the connections between brain cells, leading to the symptoms of Phelan-McDermid syndrome." (PMID 28139198, 2017). "A recurrent breakpoint within a 15 base pair region of the SHANK3 gene has been identified in three individuals with Phelan-McDermid syndrome." (PMID 18505557, 2008). "SHANK3 is recognized to be strongly associated to ASD in large population studies and is the primary genetic driver of the neurodevelopmental disability seen in Phelan McDermid syndrome." (PMID 38352654, 2024). "In our study, the 3 patients with SHANK3 gene deletion could be also diagnosed as patients of Phelan-McDermid syndrome." (PMID 38451970, 2024). "Phelan-McDermid syndrome (PMS, OMIM# 606232) results from either different rearrangements at the distal region of the long arm of chromosome 22 (22q13.3) or pathogenic sequence variants in the SHANK3 gene." (PMID 35495150, 2022). "For example, the clinical presentation of three patients (No. 88, 89, 90) who were diagnosed with Phelan-McDermid syndrome and carried different frameshift variants in SHANK3 were not exactly similar." (PMID 33176815, 2020). "Another interesting example is that of the gene SHANK3: mutations in this gene lead to a neurodevelopmental disorder known as Phelan-McDermid syndrome; to date, no pharmaceutical compounds targeting core symptoms of this human disease are available." (PMID 32741357, 2020). "In contrast, in a mouse line of Shank3B–/– (SH3 and multiple ankyrin repeat domains 3 deficiency, modeling the Phelan McDermid Syndrome), Tau reduction was not beneficial." (PMID 32661233, 2020). "In contrast to contiguous gene syndromes such as Williams syndrome, several other microdeletion syndromes have been shown recently to be caused mainly by haploinsufficiency of a single responsible gene such as MEF2C in 5q14.3 microdeletion syndrome or SHANK3 in Phelan-McDermid syndrome." (PMID 26421060, 2015). "The individuals carrying SHANK3 deletions had also manifestations of the Phelan-McDermid syndrome." (PMID 25188300, 2014). "Prenatal HDAC inhibition by VPA transiently reduces the expression of Shank3 14 days after culturing embryonic neurons, which suggests the presence of a compensatory mechanism that reduces the genetic load for ASD, in contrast to the strong impact of Shank3 mutations in Phelan-McDermid syndrome." (PMID 37873949, 2024). "SHANK3 is a scaffolding protein located at excitatory synapses, and mutations of SHANK3 (haploinsufficiency) may account for 1-2% of all ASD cases including Phelan-McDermid syndrome (PMS)." (PMID 36845137, 2023). "Phelan-McDermid Syndrome [PMS; under the Autism Spectrum Disorders (ASD) umbrella] is a rare genetic condition caused by deletion or de novo pathological variation of the long arm terminal end of chromosome 22 (location q13.3; also referred to as 22q13.3 deletion syndrome) within the Shank3 gene." (PMID 36429060, 2022). "Broadly, an increased frequency of SHANK3 CNVs in ASD patients in our study and in Chinese population suggest a higher frequency of Phelan-McDermid syndrome in DD/MR/ASD patients among East Asians." (PMID 38451970, 2024). "We obtained genetic and sleep questionnaire data from the Phelan-McDermid Syndrome International Registry (PMSIR) to estimate the frequency and age of onset of sleep problems in PMS individuals carrying a SHANK3 deletion." (PMID 30973326, 2019).
Phelan-McDermid syndrome (continued). "Individuals with r22 may present similar features as those with Phelan-McDermid syndrome (PMDS) due to 22q13.3 deletion, including the SHANK3 gene." (PMID 34777208, 2021). "Moreover, SHANK3-haploinsufficiency results in altered function, which negatively affects synaptic development and function, and its disruption contributes to ASD etiology and is also observed in individuals affected by Phelan-McDermid syndrome." (PMID 35893036, 2022).
Intellectual disability (86 papers, 2011 to 2025). "Comorbidities: intellectual disability (30%), epilepsy (20%−30%) Risk: older parents, genetic mutations (e.g., SHANK3, NLGN3)." (PMID 40521363, 2025). "Mutations or deletions in Shank3 cause Phelan–McDermid syndrome, characterized by global developmental delay, intellectual disability, and high ASD prevalence." (PMID 41226815, 2025). "Many human SHANK3 mutations map to exon 21 and are associated with moderate to severe intellectual disability." (PMID 36846568, 2023). "Copy number mutations of the SHANK3 gene can lead to Phelan–McDermid syndrome, which is a rare genetic disorder characterised by a number of developmental abnormalities, including intellectual disability, poor motor tone, and ASD-like symptomology." (PMID 36833409, 2023). "Phelan–McDermid syndrome (PMS), caused by pathogenic variants in the SHANK3 gene or 22q13 deletions, is characterized by intellectual disability, autistic features, developmental delays, and neonatal hypotonia." (PMID 36833418, 2023). "Phelan–McDermid syndrome (PMS) is a neurodevelopmental disorder characterized by developmental delay, intellectual disability, and autistic-like behaviors and is primarily caused by haploinsufficiency of SHANK3 gene." (PMID 37528484, 2023). "Within SHANK mutations in humans, SHANK3 mutations have been related to more severe intellectual disability among the other SHANKS isoforms." (PMID 35682760, 2022). "Loss of one functional copy of SHANK3 is sufficient to cause neurologic dysfunction that will manifest as learning difficulties, intellectual disability, language delay, and behavioral problems." (PMID 32546186, 2020). "Deletions of the chromosomal region containing SHANK3 cause Phelan-McDermid syndrome (22q13 deletion syndrome) characterized by autistic behaviors, intellectual disability, and epilepsy." (PMID 28469556, 2017). "Variety of point mutations and small deletions in the SHANK3 gene have been found in patients with ASDs, intellectual disability, and SCZ." (PMID 28469556, 2017). "In addition, SHANK2 and SHANK3 mutations are tightly linked with intellectual disability, while SHANK1 mutations have been identified in ASD patients with normal intelligence." (PMID 34021263, 2021). "Many SHANK3 mutations in humans affect exon 21 and are associated with intellectual disability." (PMID 34784886, 2021). "Shank3 mutations that include gene breakpoints, deletions, point mutations, missense mutations, microdeletions, and nonsense mutations are associated with moderate to severe intellectual disabilities." (PMID 29321759, 2017). "Changes in the phosphorylation state of Shank3 were of particular interest to us since Shank3 is critical for synaptic scaling up, interacts with many synaptic partners also known to be important for homeostatic plasticity, and is strongly associated with ASDs and intellectual disability." (PMID 35471151, 2022). "Mutations in SHANK3 have been strongly associated with ASD, intellectual disability, and Phelan−McDermid syndrome." (PMID 40330750, 2025). "Mutations in SHANK3, a scaffolding protein located postsynaptically at excitatory synapses, are associated with ASD, schizophrenia, and intellectual disability in humans." (PMID 40755426, 2025). "Direct sequencing of the SHANK3 gene has shown mutations in 0.5% of individuals with ASD, 0.5 to 1% of individuals with intellectual disability, and 0.5% of individuals with schizophrenia, supporting the significant clinical heterogeneity according to DSM-5." (PMID 37810596, 2023). "Due to the high frequency of mutations in the synaptic scaffolding protein SHANK3 (more than 1 in 50) in patients with ASD and intellectual disability, mutation screening of SHANK3 has been suggested for consideration in clinical practice." (PMID 33945465, 2021). "Defects in SHANK genes, but especially SHANK3, can be causative for idiopathic ASD and ASD-associated syndromes such as the PMDS, but also schizophrenia and intellectual disability." (PMID 34784886, 2021).